FN3KRP (fructosamine 3 kinase related protein)
Description:
Ketosamine-3-kinase involved in protein deglycation by mediating phosphorylation of ribuloselysine and psicoselysine on glycated proteins, to generate ribuloselysine-3 phosphate and psicoselysine-3 phosphate, respectively. Ribuloselysine-3 phosphate and psicoselysine-3 phosphate adducts are unstable and decompose under physiological conditions. Not able to phosphorylate fructoselysine.
Synonyms: FLJ12171; FN3KL
Tractability: PROTAC: ubiquitination databases record sites on it; its protein half-life has been measured.
Target class: Enzyme; Transferase
Gene: Protein-coding gene on chromosome 17 (82,716,706 to 82,730,328, forward strand). Ensembl gene ENSG00000141560.
Subcellular location (Human Protein Atlas): Nucleoplasm
Pathways (Reactome):
Metabolism of proteins: Gamma carboxylation, hypusinylation, hydroxylation, and arylsulfatase activation
Gene Ontology:
Molecular function: protein-ribulosamine 3-kinase activity; kinase activity
Biological process: post-translational protein modification
Cellular component: cytosol
Genetic constraint (gnomAD): Loss-of-function variants: 33 observed, 31.31 expected, observed/expected ratio (o/e) 1.05, 90% interval 0.8 to 1.41. The upper end of that interval is the gene's LOEUF score, 1.41, which puts it in group 5 of 6, group 1 being the genes least tolerant of losing a copy. Missense variants: 430 observed, 409.33 expected, observed/expected ratio (o/e) 1.05, 90% interval 0.97 to 1.14. Synonymous variants: 157 observed, 157.28 expected, observed/expected ratio (o/e) 1, 90% interval 0.88 to 1.14.
Homologues: Orthologues: chimpanzee FN3KRP (99% identical), macaque FN3KRP (96% identical), mouse Fn3krp (89% identical), rabbit FN3KRP (88% identical), guinea pig FN3KRP (87% identical), dog FN3KRP (87% identical), pig FN3KRP (84% identical), zebrafish fn3krp (70% identical), tropical clawed frog fn3k (55% identical), Caenorhabditis elegans Y116A8C.25 (35% identical). Paralogues in human: FN3K (64% identical).
Diseases named in the same sentence as FN3KRP in open-access papers:
FN3KRP is named in the same sentence as 5 diseases in open-access papers, as found by Europe PMC text mining. Sharing a sentence is not in itself a finding about the gene and the disease. The quoted sentences say what the papers report.
diabetes (1 paper, 2022). "Recent researches suggest that FN3KRP polymorphisms have protective effects against diabetes and cardiovascular diseases, which share common risk factors with pregnancy disorders such as vascular dysfunction and high glucose levels." (PMID 35884785, 2022).
Hyperglycemia (1 paper, 2014). An increased concentration of glucose in the blood. "A notable exception was FN3KRP, a gene related to deglycation of proteins and thus possibly protective against hyperglycemia." (PMID 25494627, 2014).
pregnancy disease (1 paper, 2022). "Considering that it is the first study indicating a significant association between FN3KRP and pregnancy disease, RPL, our results suggest the need for further investigation of the role of FN3KRP in pregnancy loss." (PMID 35884785, 2022). "In particular, the role of FN3KRP in pregnancy disorders has not previously been explored." (PMID 35884785, 2022).
cardiovascular diseases (1 paper, 2022). "In particular, FN3KRP rs1046875 G>A protects against cardiovascular diseases through HbA1c, glycated hemoglobin, and affects the binding affinity of miR-34a which acts as a suppressor of angiogenesis and glucose metabolism." (PMID 35884785, 2022).
FN3KRP also shares sentences with these, for which no sentence is quoted: cancer (1 paper).